MMP3 (matrix metallopeptidase 3)
Diseases named in the same sentence as MMP3 in open-access papers (continued):
Sharing a sentence is not in itself a finding about the gene and the disease.
Stroke (continued). "We previously reported significantly increased MMP-3 levels in the ipsilesional hemisphere of mouse brains at 48 h post-stroke." (PMID 39000490, 2024). "Our RNA-seq analysis showed that genetic ablation of MMP-3 in our mouse model of stroke had a significant effect on EMT/EndMT gene expression in the brain during the subacute stroke phase when BBB dysfunction starts." (PMID 39000490, 2024). "MMP-3 is upregulated within several hours after stroke and this corresponds with the initial opening of the BBB." (PMID 39000490, 2024). "We are the first to use RNA-sequencing analysis to identify global transcripts differentially expressed in MMP-3 KO mouse brains in the subacute stage of stroke." (PMID 39000490, 2024). "MMP-3 KO altered gene expression signatures for neuroinflammation, apoptosis, EndMT, and integrin signaling during the subacute stroke phase, which coincides with BBB breakdown and IR injury." (PMID 39000490, 2024). "Female MMP-3 KO stroke brains showed downregulation of the macrophage classical activation signaling genes Tnf and Tnfsf9, and decreased expression of the acute phage response genes Tnfrsf1a, Jun, Tnfrsf1b, Il6, Tnf, and Fos." (PMID 39000490, 2024). "We performed further analysis of DEGs in female stroke brains to better assess the effects of MMP-3 KO during the subacute stroke phase." (PMID 39000490, 2024). "When compared to WT stroke brain controls, male MMP-3 KO stroke brains had decreased expression of 78 inflammation-related genes (NES= −1.88), while female MMP-3 KO stroke brains showed downregulation of 59 inflammation-related genes (NES= −2.56)." (PMID 39000490, 2024). "We observed a sex-specific downregulation of other chemokines and Nfkb1 upon MMP-3 deletion, but this was unsurprising considering well-established sex differences in the inflammatory response to stroke." (PMID 39000490, 2024). "Compared to brains from MCAO/R WT mice, brains from MMP-3 KO mice had significantly smaller infarct sizes measured at 48 h post-stroke." (PMID 39000490, 2024). "Previous studies have shown that MMP3 contributes to the tPA-induced hemorrhagic transformation and worsens functional outcomes after hyperglycemic stroke, partially due to MMP3 degrading tight junction proteins." (PMID 37611902, 2024). "In this study, we analyzed bulk RNA harvested from whole brains to assess the effect of MMP-3 KO on stroke pathophysiology." (PMID 39000490, 2024). "We also compared the transcriptomes of female MMP-3 KO mouse stroke brains (n = 4) to those of female WT stroke brains (n = 4) (MMP-3 KO MCAO vs. WT MCAO)." (PMID 39000490, 2024). "Like male brain samples, PCA was able to clearly separate the transcriptomes of female MMP-3 KO stroke brains from those of female WT stroke brains." (PMID 39000490, 2024). "Similar analysis of genes in the Disease and Function categories indicated that female MMP-3 KO stroke brains had decreased expression of leukocyte migration genes Ccr1, Pecam1, Mmp9, Ccl6, Icam2, and Ccl11." (PMID 39000490, 2024). "Both male and female MMP-3 KO stroke brains showed decreased expression of genes involved in fibulin signaling (Fbln1, Fbn1, Fbln2, Fbln5), which are known to induce EMT during embryonic development." (PMID 39000490, 2024). "Inhibition of matrix metalloproteinase-3 (MMP-3) emerges as a promising therapeutic approach to mitigate IR-induced stroke injury." (PMID 39000490, 2024). "We performed IPA of transcriptome data from brains of female MMP-3 KO and female WT mice at 48 h post-stroke." (PMID 39000490, 2024). "Here we present the first comprehensive analysis of gene networks in the brain altered by MMP-3 KO that correlate with reduced infarct volume following stroke." (PMID 39000490, 2024). "It is unlikely that MMP-3 regulates the genes identified in our study to the same degree across all cell types in the brain following stroke." (PMID 39000490, 2024).
Stroke (continued). "Nevertheless, our research suggests that MMP-3 is a pro-apoptotic factor in the stroke-afflicted brain." (PMID 39000490, 2024). "Functional pathway analysis revealed that inflammation, integrin cell surface signaling, endothelial- and epithelial-mesenchymal transition (EndMT/EMT), and apoptosis gene signatures were decreased in MMP-3 KO stroke brains." (PMID 39000490, 2024). "We compared pathway enrichment results between male and female mouse brains to assess potential sex differences in the effects of MMP-3 inhibition on stroke infarct size." (PMID 39000490, 2024). "We conducted Ingenuity Pathway Analysis (IPA) of DEGs to further interrogate cellular pathways affected by MMP-3 KO in male stroke brains." (PMID 39000490, 2024). "We also found that human neural stem cell (hNSC) transplantation reduced MMP-3 levels in aged mouse stroke brains." (PMID 39000490, 2024). "Female MMP-3 KO stroke brains also had decreased expression of blood cell adhesion genes Pecam1 and Icam2, and decreased expression of inflammatory response genes Ccr1, Cxcl1, Mmp9, Il4ra, Il6, and Il1rn." (PMID 39000490, 2024). "Our study underscores MMP-3 inhibition as a promising therapeutic strategy, impacting multiple cellular pathways following stroke." (PMID 39000490, 2024). "Further analysis of the TPM values for these genes from WT and MMP-3 KO male stroke brains confirmed our observation from the volcano plot (Figure A4B)." (PMID 39000490, 2024). "Nevertheless, MMP-3 deletion significantly downregulated several inflammatory pathways in both males and females during the subacute stroke phase." (PMID 39000490, 2024). "MMP-3 levels sharply increase within several hours after stroke; this coincides with the initial stages of BBB disruption." (PMID 39000490, 2024). "We found 889 downregulated and 2879 upregulated genes in female MMP-3 KO brains when compared to female WT brains at 48 h post-stroke with a fold change >1.5 into either direction (FDR < 0.05)." (PMID 39000490, 2024). "Further analysis of DEGs from our RNA-seq data revealed that MMP-3 KO decreased expression of genes related to EMT in male mouse brains during the subacute stroke phase." (PMID 39000490, 2024). "Specifically, we investigated the impact of MMP-3 knockout (KO) on stroke pathophysiology using RNA sequencing (RNA-seq) of stroke brains harvested 48 h post-MCAO." (PMID 39000490, 2024). "In both sexes, MMP-3 KO decreased inflammatory gene signatures in the brain during the subacute stroke phase." (PMID 39000490, 2024). "Key EMT-related genes that were downregulated in female MMP-3 KO stroke brains included Fbln5, Fbln1, Fbln2, and Tgfb1." (PMID 39000490, 2024). "In male MMP-3 stroke brains, RNA-seq analysis identified 252 downregulated and 81 upregulated genes." (PMID 39000490, 2024). "In both male and female stroke brains, we found that MMP-3 KO decreased the expression of Itga10 and Itgb3, which encode the subunits that form integrin αvβ3." (PMID 39000490, 2024). "Chemokines such as Cxcl5 and Ccr7 were also downregulated in both male and female stroke brains upon MMP-3 KO." (PMID 39000490, 2024). "Genes related to inflammation such as Ccl5, Cxcl5, Il1a, Tnfsf10, Nfkb1, Tnfrsf1b, Ccr7, Tnfrsf9, Ccl7, Il1b, Il6, and Ccl24 were also downregulated upon MMP-3 KO in male stroke brains." (PMID 39000490, 2024). "Clustering analysis of DEGs in male and female stroke brains revealed that MMP-3 KO decreased expression of genes that belong to the adhesion and leukocyte extravasation pathway such as Esam, Icam1, Icam2, Mcam1, and Pecam1." (PMID 39000490, 2024). "We found 252 downregulated and 81 upregulated genes in MMP-3 KO stroke brains with a fold change >1.5 in either direction (FDR < 0.05)." (PMID 39000490, 2024).
Stroke (continued). "Although we observed similar trends in depleted pathways between male and female MMP-3 KO stroke brains, females overall showed a more profound downregulation of gene signatures as reflected in their more negative z-scores and enrichment scores." (PMID 39000490, 2024). "Our GSEA results of male mouse brains revealed depletion of 71 genes related to both extrinsic and intrinsic apoptotic signaling pathways upon MMP-3 KO in the subacute stroke phase (NES = −1.63)." (PMID 39000490, 2024). "MMP-3 and MMP-7 are also related to carotid atherosclerosis and stroke, with some polymorphisms causing variability in the risk of suffering from stroke." (PMID 37762627, 2023). "In stroke, biphasic BBB breakdown is caused by activated matrix metalloproteinase (MMP)-2, MMP-3 and MMP-9." (PMID 36224611, 2022). "The most significantly upregulated genes, including Lpl, Spp1, Cd36, Mmp2, and Mmp19, and the most highly enriched genes, including Cd5l, Mmp3, Mmp12, and Mmp13, indicate a pronounced disturbance in lipid homeostasis in infarcts at 7 weeks after stroke." (PMID 34819339, 2022). "Further, MMP-3 reportedly exacerbates tPA-induced intracerebral hemorrhage (ICH) post-stroke in thrombotic MCAO mouse brains." (PMID 34299322, 2021). "Consistent with increased IL-17A levels, we detected a significant upregulation of Cxcl1 and Mmp3 transcripts in the whole brain mRNA and a significant increase in absolute numbers of neutrophils at day 3 post-stroke in Il10−/− mice, respectively." (PMID 34772416, 2021). "It has been demonstrated that protein and activity levels of MMP-3 and -9 are increased after stroke and MCAO." (PMID 31261992, 2019). "Reduced IgG extravasation and reduced MMP-9 and MMP-3 activity suggested that 1.0 mg/kg L-902,688 reduced stroke-induced BBB damage." (PMID 29527151, 2018). "Because MMP-3 and MMP-9 are major contributors to BBB damage after stroke, we wanted to see if the reduced BBB damage evidenced by reduced IgG extravasation was associated with reduced MMP-3/MMP-9 activity and protein levels." (PMID 29527151, 2018). "With immunoblotting, qRT-PCR, and/or a fluorescence resonance energy transfer (FRET)-based activity assay, we next measured MMP-3/-9 since they are key effectors of BBB breakdown in stroke." (PMID 29527151, 2018). "EP4 receptor activation similarly reduced stroke-induced MMP-9 and MMP-3 activity, particularly in the cortex, and stroke-induced MMP-9 mRNA levels." (PMID 29527151, 2018). "H-FABP, IL-1ra, IL-8, S100β, CRP and Troponin I concentrations were also significantly increased whereas MMP3 and E-selectin concentrations showed a reduction in stroke patients compared to controls (0.001<p<0.05)." (PMID 23028472, 2012). "Additionally, MMP-3 and MMP-12 expression is significantly upregulated post-stroke: MMP-3 activates pro-MMP-9, amplifying the proteolytic cascade; MMP-12 further exacerbates neurovascular injury by promoting inflammatory cell infiltration." (PMID 41480312, 2025). "Our RNA-seq analysis revealed significant downregulation of gene expression signatures for neuroinflammation, endothelial- and epithelial-mesenchymal transition (EndMT/EMT), and apoptosis in MMP-3 KO mouse stroke brains compared to MMP-3 wild-type (WT) controls." (PMID 39000490, 2024). "We hypothesized that inhibition of MMP-3 may improve stroke outcome through several other biochemical and cellular pathways in addition to activation of other latent MMPs." (PMID 39000490, 2024). "In addition, our IPA results showed that MMP-3 KO reduced gene expression related to adhesion of blood cells, integrin signaling, leukocyte migration, and leukocyte extravasation at 48 h post-stroke." (PMID 39000490, 2024). "This suggests that females may have greater induction of MMP-3 expression in the brain following stroke than males do." (PMID 39000490, 2024).
Stroke (continued). "Notably, RNA-seq analysis showed that MMP-3 KO altered expression of 333 genes (252 downregulated) in male stroke brains and 3768 genes (889 downregulated) in female stroke brains." (PMID 39000490, 2024). "We analyzed bulk RNA from whole brain tissue, so it remains unclear whether MMP-3 KO downregulated genes for apoptosis in neurons and ECs or in other cell types within the brain during the subacute stroke phase." (PMID 39000490, 2024). "In addition, in a mouse stroke model, tPA treatment selectively induced MMP-3 expression in injured endothelial cells." (PMID 39273389, 2024). "Furthermore, female MMP-3 KO stroke brains showed decreased expression of apoptosis signaling genes Casp6, Tnfrsf1b, Tnfrsf1a, and Tnf, and downregulated expression of matrix metalloprotease genes Mmp14, Mmp9, and Mmp11." (PMID 39000490, 2024). "Moreover, pharmacological inhibition of MMP-3 improves stroke outcome and decreases hemorrhagic transformation in a diabetic female rat model of stroke." (PMID 39000490, 2024). "However, the data showed a greater magnitude of pathway depletion in female MMP-3 KO stroke brains than in male MMP-3 KO stroke brains for all gene sets." (PMID 39000490, 2024). "Interestingly, our RNA-seq analysis indicated downregulation of genes for both the intrinsic and extrinsic apoptosis pathways in the brains of male and female MMP-3 KO mice during the subacute stroke phase." (PMID 39000490, 2024). "Overall, our results suggest that MMP-3 inhibition may benefit stroke outcome by reducing expression of transforming growth factor and fibulin signaling factors within the brain to inhibit EndMT." (PMID 39000490, 2024). "Nevertheless, our analysis suggests that MMP-3 inhibition may decrease stroke infarct volume by dampening the expression of inflammatory mediators that attract peripheral immune cells to the ischemic lesion and potentiate IR injury." (PMID 39000490, 2024). "In addition to GSEA, IPA of RNA-seq data revealed downregulation of apoptosis signaling (z = −0.6) in the canonical pathway category for female MMP-3 KO mice in the subacute phase of stroke." (PMID 39000490, 2024). "We assessed the effects of MMP-3 genetic deletion on infarct volume in stroke brains." (PMID 39000490, 2024). "Similarly, genes involved in integrin cell surface interactions including Itga10, Itgb3, Vcam1, Itgb1, Itgae, Itgb7, Itga1, Itga5, Icam1, Itgb2, Pecam1, and Icam2 were depleted in male MMP-3 KO stroke brains." (PMID 39000490, 2024). "In addition to Il6, we also observed downregulation of Il1a and Il1b in male stroke brains, and downregulation of Il1r1 in female stroke brains upon genetic ablation of MMP-3." (PMID 39000490, 2024). "Our functional analysis revealed several enriched or depleted pathways in MMP-3 KO stroke brains." (PMID 39000490, 2024). "In female stroke brains, MMP-3 deletion downregulated 889 genes and upregulated 2879 genes." (PMID 39000490, 2024). "MMP-3 KO significantly reduced brain infarct size following stroke." (PMID 39000490, 2024). "Only a few studies have tested the circulating levels of MMP‐3 after stroke." (PMID 37721534, 2023). "Furthermore, rt-PA treatment induced MMP-3 selectively in ECs at the ischemic damaged area in a mouse stroke model, and MMP-3 was increased in a postmortem human stroke brain." (PMID 26834557, 2016). "Furthermore, using a mouse stroke model, tPA treatment induced MMP-3 expression selectively in ECs damaged by ischemia." (PMID 23565108, 2013). "Thus, MMP-3 inhibition may reduce stroke infarct volume by decreasing the expression of genes that induce BBB dysfunction." (PMID 39000490, 2024). "On the other hand, downregulation of extrinsic apoptosis factor gene expression by MMP-3 KO may reduce stroke infarct volume by blocking apoptosis of neurons and cells of the BBB induced by death receptor signaling during the inflammatory response following the initial ischemic insult." (PMID 39000490, 2024).
Stroke (continued). "Thus, MMP-3 inhibition may reduce infarct volume after stroke by decreasing the expression of genes required for leukocyte adhesion and extravasation through the BBB, thereby limiting IR injury caused by prolonged cytotoxic inflammation." (PMID 39000490, 2024). "MMP-2, MMP-3, MMP-9, MMP-13, and MT1-MMP have all been identified in neuronal nuclei and gelatinases (MMP-2 and MMP-9) and MMP-3 have been implicated in the progression of infarct volume and neuronal death in animal models of stroke and ischemic stroke patients." (PMID 26925194, 2016). "rt-PA treatment did not alter ICB associated with stroke in mice deficient in plasminogen and MMP-3, suggesting that plasmin may be required to activate MMP-3 by rt-PA in ECs during stroke." (PMID 26834557, 2016). "Nevertheless, our analyses clearly demonstrate that MMP-3 KO attenuated EndMT- and EMT-related gene expression in the brain during the subacute stroke phase, which correlated with reduced infarct volume." (PMID 39000490, 2024). "Bioinformatic analysis of whole stroke brain RNA-seq data revealed depletion of gene signatures related to EMT, neuroinflammation, apoptosis, and integrin cell surface interactions upon MMP-3 deletion in both males and females." (PMID 39000490, 2024). "Key EMT-related genes that were downregulated in MMP-3 KO males included Fbn1, Fbln1, Tgfb1, Tgfbr3, Snai2, and Fgf2, while female MMP-3 KO stroke brains showed downregulation of Fbln5, Fbln1, Fbln2, and Tgfb1." (PMID 39000490, 2024). "TIMP-3 can inhibit MMP-2, MMP-3, and MMP-9 which regulate ECM structure and vascular remodelling and consequently affect hypertension-induced stroke." (PMID 35444693, 2022). "While the role of MMP-3 in hemorrhagic transformation in rodents has been reported, the critical role of MMP-3 in BBB integrity and function remains understudied in cerebral IR injury post-stroke." (PMID 34299322, 2021). "In this study, we observed that MMP-3/9 and VEGFA expression were downregulated in EC-TXNIP KO mice with HG and tPA-reperfusion, which correlates with improved BBB function after embolic stroke." (PMID 34681207, 2021). "Our results support the concept that tPA-reperfusion in HG mice promotes HT and BBB damage after embolic stroke, possibly through TXNIP and upregulating MMP-3/9, and VEGFA expression." (PMID 34681207, 2021). "Covariates in the final MBDA-based CVD risk score were age, diabetes, hypertension, tobacco use, history of CVD (excluding MI/stroke), MBDA score, leptin, MMP-3 and TNF-R1." (PMID 33276814, 2020). "These mice also developed birefringent crystals in the infarct in the weeks after stroke and had abundant expression of MMP-2, MMP-3, and MMP-8 in the area of liquefaction seven weeks following stroke." (PMID 30417081, 2018). "There was chronic and abundant expression of MMP-2, MMP-3, and MMP-8 in the area of liquefactive necrosis following stroke compared to the equivalent area of infarction in the heart." (PMID 30417081, 2018). "We recently showed that genetic deletion or pharmacological blockade of the EP1 receptor results in a dramatic reduction in stroke injury and BBB permeability, which correlated with reduced levels of MMP-3 and MMP-9." (PMID 29527151, 2018). "IL-18 is also present in the area of liquefactive necrosis for at least eight weeks following stroke, and there are also strikingly high levels of MMP-2, MMP-3, and MMP-8." (PMID 30417081, 2018). "We found that EP4 receptor activation with L-902,688 potently reduces levels of some of the key mediators of stroke-induced BBB damage including IL-1β, IL-6, MMP-3, and MMP-9." (PMID 29527151, 2018). "miR-320 targets ETS2, a transcription factor that regulates the expression of several genes important to leukocyte extravasation post-stroke including MMP-9, MMP-3, MMP-13, ANGPT1, and TNF." (PMID 24911610, 2014).